CD4 (CD4 molecule)
Diseases named in the same sentence as CD4 in open-access papers (continued):
Sharing a sentence is not in itself a finding about the gene and the disease.
tumor (continued). "Previous studies have documented the effects of PGE2 on the various CD4+ T cell functions, but little is known about its impact on cytotoxic CD8+ T lymphocytes, the immune cells responsible for eliminating virally infected and tumor cells." (PMID 24918932, 2014). "The ROI of tumor-bearing mice was compared every week between vaccinated mice with or without CD8+/CD4+ T-cell depletion." (PMID 25153727, 2014). "In contrast to CD4+ “helper” T cells, CD8+ T cells are responsible for direct cell mediated cytotoxicity following activation by APCs and are thought to play a central role in the anti-tumor immune response." (PMID 24883190, 2014). "This greater probability of tumor improvement was seen without any noted impairment in CD4 count recovery." (PMID 24632813, 2014). "Depletion of CD4+ T cells failed to generate the same level of antitumor protection as that seen in the isotype control group, and only some animals remained tumor-free." (PMID 25153727, 2014). "Thus, in CD4+ T cell immune responses to tumors, the MHC class II status of the tumor cells is of importance." (PMID 24782871, 2014). "Instead, complete tumor eradication was only observed when combined vaccination and surgery was performed in the absence of CD4 T cells." (PMID 25186961, 2014). "Effector Th1 type helper CD4+ T cells with the ability to secrete IFN-γ and TNF-α can act as regulators in anti-tumour immunity and provide ‘help’ for the development of potent anti-tumour CTLs by supporting their expansion and memory development." (PMID 24520352, 2014). "A treatment regimen that shows good tumor response without undue suppression of CD4 count is an ideal option for the treatment of AIDS related KS." (PMID 24632813, 2014). "Moreover, the immunosuppressive function Treg cells exert on CD4+ and CD8+ T-cells have been identified as a crucial variable limiting an effective anti- tumor immune response." (PMID 25365237, 2014). "Because CD4+ T cells aid CD8+ T cells, it is possible that in situations where NKT cells interrupt CD8+ T cell-immunity and tumor rejection, NKT cell suppression of naïve CD4+ T cells may contribute." (PMID 25389427, 2014). "Similarly, the specific response of CD4- and/or CD8-positive cells to tumour can be triggered by Hsp70 released from dying or alive cancer cells." (PMID 24797019, 2014). "There are several studies implying that the relative amount of CD3+, CD4+, CD8+, and CD56+ may be important and by reducing the tumor burden." (PMID 24720900, 2014). "A subsequent phase III randomized, placebo-controlled trial revealed that tumor cell numbers and peritoneal levels of VEGF decreased with catumaxomab, whereas the activation status of CD8+ and CD4+ T-cell populations increased more than two-fold after treatment." (PMID 25331657, 2014). "In this model where Rgs5 is inactivated, adoptive T-cell transfer results in massive infiltration of CD8+ and CD4+ lymphocytes within the tumor, whereas wild type tumors showed no significant increase of intratumoral immune cells." (PMID 24765614, 2014). "The results demonstrated that the number of CD4+ and CD8+ T lymphocyte cells in the peripheral blood of tumor-bearing mice treated with Ad-hLF significantly increased compared with that of the control group (P<0.05) and was near to that of normal mice (P>0.05)." (PMID 24520300, 2014). "It should be stressed that in the control (untreated) group of mice, we found a promising negative correlation of tumor growth with CD4+ lymphocyte accumulation and an upward trend for a positive correlation of tumor growth with MDCS accumulation." (PMID 24608924, 2014).
tumor (continued). "In this study, we showed that EGFR inhibition augmented PGE2 production by Sa-3 tumor cell, and that COX-2 inhibitor could restore the suppression of antigen-specific CD4+ T cell responses." (PMID 25240937, 2014). "Furthermore, a significant positive correlation was observed between CD4 and CD8 expression in the tumor parenchyma and stroma (both P<0.001)." (PMID 25289108, 2014). "To analyze the correlation between Treg abundance and the abundance of CD8+ T cells or CD4+ T cells in the PDA microenvironment, we also investigated the relationship between the proportion of tumor-infiltrating CD8+ T cells or Tregs and clinicopathologic characteristics." (PMID 24637664, 2014). "Athymic nude mice and Balb/c mice depleted of CD4+ or CD8+ T-cells were not protected against MethA tumor cell growth after immunization with D2SC/1–MethA hybrids." (PMID 25340039, 2014). "We detected significantly more CD8+ than CD4+ T cells in both well-differentiated (p<0.0001) and poorly differentiated (p = 0.001) tumors, confirming our prior finding that CD8+ T cells are enriched in the tumor microenvironment relative to the blood." (PMID 24794217, 2014). "The immunophenotype of tumor cells is CD3+, CD7−, CD4+/CD8−, and CD25+." (PMID 25587470, 2014). "As an initial test of this hypothesis, we challenged B6 mice with the various live OVA expressing tumor lines and compared their ability to expand OVA specific CD4 T cells (OT-II cells) or CD8 T cells (OT-1 T cells) in vivo." (PMID 24614600, 2014). "Additionally, mice were depleted of CD4 and/or CD8 T lymphocytes during vaccination to assess their involvement in vaccine induced anti-tumor immunity." (PMID 25186961, 2014). "Nevertheless, the CRTE6E7L2 DNA vaccine conferred 100% protection against subcutaneous TC-1 tumor challenge in both CD4-depleted mice and non-depleted mice." (PMID 24594273, 2014). "Non-traditional CD4+CD25–CD69+ T cells were found to be involved in disease progression in tumor-bearing mouse models and cancer patients recently." (PMID 24984576, 2014). "The combination of allo-BMT+TT has been proven to be a novel strategy for suppressing tumor growth, this strategy restoring T-cell function and improving the percentage of CD4+ (but not CD8+) T cells in the short term after BMT." (PMID 24847950, 2014). "CD4 T cell depletion was transient and had returned to baseline levels by day 81 when surviving mice were rechallenged with parental tumour (data not shown)." (PMID 25186961, 2014). "We propose that binding of the fusion protein with both tumor cells and DCs improves phagocytosis of parts of tumor cells by DCs, and therefore any tumor antigen can be processed and loaded on both MHC class II and MHC class I molecules, and presented to CD4+ and CD8+ T cells." (PMID 24565018, 2014). "There were no changes in the proportion of activated (ICOS+) CD4 or CD8 T cells in the different surgical debulking groups either in the tumor itself or in the peripheral lymphoid organs (data not shown)." (PMID 25518732, 2014). "Protection was abrogated by depletion of CD8+ but not CD4+ T cells, indicating that tumor-specific CD8 T cells were critical mediators of tumor immunity." (PMID 24982761, 2014). "We also found a major increase in absolute numbers and percentage of immature CD4+ non-plasmacytoid DCs in mice at ST but not TT following tumor inoculation." (PMID 24575090, 2014). "However, it must be determined what the role of CD4+ and CD8+ T-cells is in this treatment and how the animals are clearing secondary tumor challenges." (PMID 24949488, 2014). "Already 15 years ago CD4+ Th cells of the Th1 (predominantly IFNγ) and Th2 (predominantly IL-4) cells as well as CD8+ T cells have been shown to play a key role for an effective anti-tumor response." (PMID 24885059, 2014).
tumor (continued). "Based on the observation that fucoidan functioned as an adjuvant to activate OVA-specific CD4 and CD8 T cells, we further investigated whether this response can protect mice grafted with OVA-expressing B16 tumor cells." (PMID 24911024, 2014). "Furthermore, we observed that culture supernatants from Mo/Ma co-incubated with CD4+ or CD8+ TIS-T lymphocytes have pro-angiogenic effects as determined by their increased tubulogenesis and tumor cell pro-survival potential." (PMID 25375372, 2014). "Although HNSCC-bearing mice are characterized by an increase in conventional CD4+ and CD8+ T cells in tumor-draining lymph nodes compared to premalignant-bearing and control mice, these cells exhibit functional deficits and have significantly decreased proliferative capacity." (PMID 24698959, 2014). "Myeloid-derived suppressor cells down-modulate naïve CD4+ and CD8+ T lymphocyte trafficking and re-circulation, inhibit CD8+ T cell tumor and tumor-draining lymph node infiltration, suppress NK cells and promote the conversion of naive CD4+ T cells into induced Tregs." (PMID 25072019, 2014). "We thought to use total BM as the source of samples for this study since our institution has RNA bank available and the study of the T cell compartment inside tumor BM environment, without manipulation of CD4 subpopulations by sorting looked appealing." (PMID 25099367, 2014). "In WT mice receiving Fab anti-CD200R, no tumor cells are detectable following immunotherapy, and CD4+ cells produced increased TNFα/IL-2/IFNγ on stimulation with EMT6 in vitro." (PMID 25409195, 2014). "In the tumor models where it has been tested, be they MHC IINEG or MHC IIPOS, there was an apparent need for tumor-specific antigen to be presented by host APC to stimulate naïve (but not memory) CD4+ T cells." (PMID 24782871, 2014). "On the other hand, direct killing of MHC IIPOS tumor cells by cytotoxic CD4+ T cells was demonstrated not to induce bystander killing." (PMID 24782871, 2014). "In this context, the question that arises is what is the reason why the responses mediated by CD8+ cytotoxic T-lymphocytes are not effective in eradicating the tumor and how can the CD4+ T-cells be involved in neoplastic progression of this disease?" (PMID 24672781, 2014). "At ST, there was an increase in absolute number and a decrease in the percentage of CD86− mature CD4+ non-plasmacytoid DCs in response to tumor, but no significant changes were observed at TT." (PMID 24575090, 2014). "Indeed, immunological studies demonstrated that cured mice developed both anti-tumor CD8+ and CD4+ T cell immunity." (PMID 24600588, 2014). "Indeed, we found that the majority of both CD4+ and CD8+ T cells in the tumor microenvironment of PDA expressed PD-1, in contrast to the rarity of PD-1 expressing T cells in peripheral blood." (PMID 24794217, 2014). "We did see a reduced percentage of CD86+ mature CD4+ non-plasmacytoid DCs at ST but not at TT following tumor inoculation." (PMID 24575090, 2014). "In addition, CD8 responses have been shown to be responsive to OX40 stimulation and both CD4 and CD8 T cells are needed for αOX40-mediated tumor immunity." (PMID 24682539, 2014). "We hypothesized that triple therapy will result in higher CD4+ and CD8+ tumor infiltrating lymphocytes." (PMID 25013914, 2014). "In vivo CD4 and CD8 depletion revealed that both T cell subsets contributed to anti-tumor efficacy." (PMID 25328681, 2014). "CD4 T cells exhibited no change in the surface expression of CD3ε between the tumor, draining lymph node and spleen." (PMID 24614600, 2014). "For a long time, cytotoxic CD8 lymphocytes have been considered the main mediators of tumor immune surveillance, while CD4 lymphocytes either have not been evaluated or have been associated with suppression of anti-tumor immune response." (PMID 25432519, 2014). "Other work also suggests that low CD4 counts in the tumor or in peripheral blood are a negative prognostic factor in early or metastatic breast cancer." (PMID 25432519, 2014).
tumor (continued). "While CD4+ T cell-depletion did reduce the E6 and E7-specific CD8+ T cell response, it remained sufficient to prevent subcutaneous tumor growth and to eliminate circulating tumor cells in a model of metastatic HPV-16+ cancer." (PMID 24594273, 2014). "In CD200R1KO mice cured (tumor-free for >300 d) by surgical tumor resection and immunotherapy, CD4+ cells, rather than effector CD8+ cells, were critical for protection." (PMID 25409195, 2014). "The activation of CD4+ T cells contributes to the secretion of immune regulatory cytokines, including IL-2, IL-12, and IFN-γ, which in turn facilitate an elevation in the cytolytic CD8+ T cell responses, thereby inducing tumor cell death." (PMID 25412106, 2014). "Albeit not as effective as in fully immune-competent animals, PROSTVAC immunotherapy in the absence of CD4 T cells significantly reduced tumor growth as compared to CD4-depleted animals (VFF + anti-CD4 vs. anti-CD4)." (PMID 25328681, 2014). "Subsequent TIL analysis revealed that PROSTVAC dosing had, even in the absence of CD4 T cells, recruited CD8 effector T cells into the tumor suggesting that PROSTVAC immunotherapy activated and recruited CD8 T cell infiltration independently of CD4 T cell help (VFF + anti-CD4)." (PMID 25328681, 2014). "B cells are required for optimal CD4 and CD8 T cell tumor immunity." (PMID 25026291, 2014). "In addition, fewer CD4 T cells infiltrated the tumor of CD8-depleted animals, suggesting that CD8 T cells aid in the recruitment of CD4 T cells into the tumor." (PMID 25328681, 2014). "Accordingly, we found that Tg-mediated ER stress decreased the number and the activation of tumor-infiltrating CD8+ T cells, and 4-PBA treatment restored these parameters although the number and the activity of CD4+ T cell and CD8+ T cells in the spleen and lymph node were not affected by ER stress." (PMID 25514597, 2014). "1×106 CD45.1+OT-II CD4 T cells isolated from CD45.1+OT-II+RAG−/− mice were adoptively transferred into CD45.2+ B6 mice and 24 hours later mice were challenged with MCA-205, MCA-205-OVA, MCA-205-E1A-Δp300-OVA, and MCA-205-E1A-OVA tumor lines." (PMID 24614600, 2014). "Despite the lack of MHC II expression on MOPC315.BM cells, primary CD4 T-cell responses (mediated by tumor-infiltrating antigen-presenting cells) can be induced, as demonstrated for the MHC II-negative parental MOPC315 cells." (PMID 25415267, 2014). "Indeed, patients with HCC often have increased Treg numbers in blood and within tumors, and the tumor-infiltrating CD8+ and CD4+ T cells have been found to be dysfunctional, suggesting a possible link between immune disruption and the pathogenesis of HCC." (PMID 24639678, 2014). "In addition, immunization with flagellin expressing cancer cells lead to impressive antigen-specific CD4 and CD8 T cell responses via NLRC4 and NAIP5 signaling and bestowed anti-tumor immunity against a secondary inoculation with tumor cells." (PMID 25071785, 2014). "Notably, the decrease in the MDSCs and the increase in the CD4+ and CD8+ T cells correlated with drastic reduction in tumor volume observed after all therapeutic treatments." (PMID 24156020, 2013). "Studies have shown tumor escape mechanisms in STAT-1−/− mice, and STAT-3 signaling was identified in the inhibitory effects of IL-10 on DC maturation and migration, and impairment of CD4+ T-cell function." (PMID 24216992, 2013). "In agreement with these previous studies, we showed that the absence of CD4+ T cells during FBL-3 formation did not significantly influence the tumor growth." (PMID 22890822, 2013). "These MHC-II-expressing FBL-3 cells could be a possible target for cytotoxic CD4+ T cells and might explain part of the CD4+ T-cell-mediated FBL-3 tumor rejection." (PMID 22890822, 2013).
tumor (continued). "CD8+ T-cell depletion alone did not influence the mean percentage of tumor-specific CD4+ T cells, suggesting that their expansion was mainly controlled by Tregs." (PMID 22890822, 2013). "In contrast, we detected substantial numbers of Tim-3-expressing CD4 T cells in both nontumor and tumor tissues." (PMID 23526963, 2013). "Experiments using a murine EGFR (mEGFR)-antagonistic antibody in a syngeneic preclinical model demonstrated that the anti-metastatic effect produced by treatment with this mab is mediated by T cells, since depletion of CD4+ and CD8+ T cells abrogated the anti-tumor effect." (PMID 23637683, 2013). "Furthermore, when these transduced DCs were injected into mice harboring murine HER-2-positive tumors, potent systemic CD4 and CD8 T cell responses along with humoral responses were generated that significantly inhibited tumor growth." (PMID 23870437, 2013). "In contrast to CD8+ T cells and Bu1a+ B cells, CD4+ T cells were near, but not within, early tumor lesions." (PMID 24040191, 2013). "Thus activation of tumor antigen-specific CD8+ CTL and CD4+ T helper cells generates antitumor immune response." (PMID 24007528, 2013). "Higher frequencies of Foxp3+CD4+ T cells are however also observed in spleen/blood and draining lymph of tumor-bearing mice and patients with cancer compared to non-tumor-bearing controls." (PMID 23874342, 2013). "However, one HIF1A TG mouse showed proliferation of CD3-positive T lymphocytes (CD-4 positive cells predominated), with a monoclonal pattern of gene rearrangement in TCR, suggesting that the tumor cells were of monoclonal origin from alpha/beta type T cells." (PMID 23593116, 2013). "In this study we report of a so far not described interaction between tumor cells and T cells, both CD4+ and CD8+ T cells." (PMID 24205259, 2013). "Specifically, in a squamous cell carcinoma model, deletion of non-malignant CD4 T cells decreased neoplastic cell progression and tumor incidence underscoring the intimate relationship between inflammation and cancer." (PMID 23949004, 2013). "This experiment suggests that CD4+ T cells can mediate potent anti-tumor effects when cytotoxic CD8+ T cells are absent but that they are tightly controlled in their activity by Foxp3+ Tregs." (PMID 22890822, 2013). "Nishikawa and colleagues also observed that CD45RO+ but not CD45RA+ tumor-specific CD4 T-cells from cancer patients were resistant to Treg suppression." (PMID 24133490, 2013). "CD4 polarisation status has not always been defined in tumour immunology studies, but both Th1 and Th2 polarised T cells have been reported to have anti-tumour function." (PMID 23717511, 2013). "Unlike in the untreated mice, increase of the spleen T cell (both CD4 and CD8) population serum T helper 1 cytokines showed activation of cell-mediated immunity by fermented mung bean that consequently helped to delay the formation of the tumor." (PMID 23710232, 2013). "Early after tumor challenge (4 days post-tumor challenge (ptc)), expansion of specific cells was only found in the CD4+ but not the CD8+ T-cell population." (PMID 22890822, 2013). "Furthermore, MF exposure was associated with activation of macrophages and dendritic cells, enhanced profiles of CD4+ T and CD8+ T lymphocytes, the balance of Th17/Treg and reduced inhibitory function of Treg cells in tumor-bearing mice." (PMID 24278103, 2013). "Consistent with the data in CD8 T cells, there was no change in the number of non-regulatory CD4 T cells in tumor-bearing mice and treated mice compared to controls." (PMID 23936036, 2013). "However, a recent study identified that in established tumor models, CD27 signaling actually promoted tumor growth, with a reduction in Treg apoptosis and production of the Treg survival cytokine IL-2 by CD4+ effector T cells (TEff)." (PMID 23840967, 2013).